LINC00261 (long independently transcribed non-coding RNA 261)
Diseases named in the same sentence as LINC00261 in open-access papers (continued):
Sharing a sentence is not in itself a finding about the gene and the disease.
endometrial cancer (4 papers, 2019 to 2023). Primary or metastatic malignant neoplasm involving the endometrium (mucous membrane that lines the endometrial cavity). "Additionally, LINC00261 is able to bind to hsa‐miR‐182, hsa‐miR‐183, hsa‐miR‐153 and hsa‐miR‐27a; further, hsa‐miR‐96 was able to regulate FOXO1 mRNA expression, suppressing cell proliferation, migration and invasion of endometrial cancer cells." (PMID 32860342, 2020).
lung adenocarcinoma (4 papers, 2018 to 2022). A carcinoma that arises from the lung and is characterized by the presence of malignant glandular epithelial cells. "Low expression of LINC00261 was associated with recurrence and poor patient survival in lung adenocarcinoma." (PMID 30597925, 2018). "Combined with the results of survival analysis and other comprehensive analysis, it suggested that there might be a regulatory relationship between LINC00261 and CDK1, so loss of LINC00261 in lung adenocarcinoma patients might lead to CDK1 overexpression." (PMID 36078096, 2022). "Study in lung adenocarcinoma (LUAD) cell lines have shown that LINC00261 overexpression obviously inhibits cell proliferation, migration and expression of DNA lesion genes, suggesting that LINC00261 is a tumour suppressor." (PMID 32558131, 2020). "Our results suggest that the decreased expression of LINC00261 promotes the overexpression of CDK1, further promotes the occurrence of lung adenocarcinoma, and affects the prognosis of patients." (PMID 36078096, 2022).
liver cancer (3 papers, 2021 to 2022). An epithelial or non-epithelial malignant neoplasm that arises from the liver. "In this study, we identified that linc00261 was down-regulated after TGF-β1 treatment, and linc00261 attenuated EMT and stem-like traits in liver cancer cells." (PMID 35123494, 2022). "To investigate the function of linc00261 in HCC, we constructed linc00261 stably overexpressionand transient knockdown models in 4 liver cancer cell lines (SMMC-7721 and Sk-hep1 for overexpression, Huh7 and MHCC-LM3 for transient knockdown)." (PMID 35123494, 2022).
endometriosis (2 papers, 2021 to 2023). The growth of functional endometrial tissue in anatomic sites outside the uterine body. "LINC00261 has shown to regulate endoderm differentiation, lung epithelial homeostasis and endometriosis." (PMID 34717566, 2021). "LINC00261 directly binds to miR-132-3p to regulate BCL2L11 expression, which inhibits the proliferation and invasion of endometriosis cells, suggesting that LINC00261 plays an inhibitory role in the occurrence and development of endometriosis." (PMID 37455911, 2023).
lymph node metastasis (2 papers, 2017 to 2019). "The expression of LINC00261 in LSCC with lymph node metastasis is significantly lower than in those without of lymph node metastasis." (PMID 31336999, 2019).
cutaneous melanoma (1 paper, 2020). A primary melanoma arising from atypical melanocytes in the skin. "Further studies are required to validate the role of MALAT1, LINC00943 and LINC00261 in cutaneous melanoma." (PMID 32993558, 2020). "MALAT1, LINC00943, and LINC00261 were selected as hub genes and are responsible for the tumorigenesis and prognosis of cutaneous melanoma." (PMID 32993558, 2020). "MALAT1, LINC00943, and LINC00261 may be closely related to tumorigenesis in cutaneous melanoma." (PMID 32993558, 2020).
esophageal cancer (1 paper, 2020). A primary or metastatic malignant neoplasm involving the esophagus. "Moreover, our own cell fractionation analysis in a panel of lung and pancreas cell lines revealed a predominant nuclear localization of LINC00261, which is supported by other studies in mouse hepatocytes, esophageal cancer cells, and lung epithelial cells." (PMID 32414223, 2020).
gallbladder cancer (1 paper, 2025). "Although the role of LINC00261 is explored in various cancers, comprehensive knowledge of its clinical potential has yet to be studied in hepatocellular, pancreatic, colorectal, and gallbladder cancers." (PMID 40136629, 2025). "Although gallbladder cancer (GBC) is considered highly dangerous, only one study to date has examined the role of LINC00261 in GBC." (PMID 40136629, 2025).
melanoma (1 paper, 2020). A malignant, usually aggressive tumor composed of atypical, neoplastic melanocytes. "Thus, the expression of MALAT1, LINC00943 and LINC00261 is increased in melanoma and may be responsible for the tumorigenesis of melanoma." (PMID 32993558, 2020).
metastatic tumor (1 paper, 2022). "We also find the expression of Linc00261 is decreased in HGSOC tissues and is further decreased in metastatic tumor tissues." (PMID 35465017, 2022).
myocardial infarct (1 paper, 2020). "Compared with AAV‐NC group, overexpression of LINC00261 significantly reduced myocardial infarct size in rats." (PMID 32558131, 2020).
ovarian carcinoma (1 paper, 2025). A malignant neoplasm originating from the surface ovarian epithelium. "Furthermore, LINC00261 has been identified as a marker for poor prognosis in ovarian cancer patients, regulating the malignant behavior of tumor cells through the sponging of miR-545-3p." (PMID 40999508, 2025).
prostate adenocarcinoma (1 paper, 2021). "Notably, LINC00261 is also upregulated in hepatic metastases from prostate adenocarcinomas." (PMID 33793068, 2021).
serous ovarian cancer (1 paper, 2022). "In this study, we demonstrate that Linc00261 is downregulation in high-grade serous ovarian cancer (HGSOC) and can inhibit cell proliferation and migration of high-grade serous ovarian cancer cells." (PMID 35465017, 2022). "Collectively, these findings suggest that Linc00261, a mediator of EMT progression, can target oncogenic miR-552, elevating ATG10 expression, to prevent high-grade serous ovarian cancer tumorigenesis and may serve as a potential novel therapeutic target." (PMID 35465017, 2022).
tumor (38 papers, 2017 to 2025). "High expression of LINC00261 was associated with large tumor size, positive lymph node metastasis, advanced TNM stages, and higher post-operative recurrence." (PMID 33842553, 2021). "LINC00261’s downregulation is associated with poor prognosis and aggressive tumor phenotypes." (PMID 40136629, 2025). "Our comprehensive literature analysis revealed that LINC00261 functions as a tumor suppressor, and its reduced expression is associated with larger tumor size, advanced tumor-node-metastasis (TNM) stages, lymphatic metastasis, and poorer overall survival rates." (PMID 40136629, 2025). "The overexpression of LINC00261 in PANC-1 stem cells suggested its potential role as a tumor suppressor in PC." (PMID 40136629, 2025). "As a tumor suppressor, LINC00261 is closely related to the clinical characteristics of patients and represents a potential therapeutic target." (PMID 41316360, 2025). "Previous studies have noted that lncRNA ZFAS1, lncRNA HOXA11-AS, and linc00261 can be used as novel tumor markers for GC screening." (PMID 37291405, 2023). "The expression levels of SELL (Log2-fold-change = −1.14) and LINC00261 (Log2-fold-change = −0.90) were significantly decreased in tumor tissues compared to the adjacent tissues." (PMID 35702258, 2022). "In this study, we report Linc00261, which is a tumor suppressor, inhibits HGSOC progression by competitively binding miR-552, elevating ATG10 expression, and then restrain EMT phenotype." (PMID 35465017, 2022). "Previously, human lncRNA DEANR1/linc00261 was described as a tumor suppressor that regulates a variety of biological processes such as cell proliferation, apoptosis, glucose metabolism and tumorigenesis." (PMID 35740417, 2022). "LINC00261 has been widely reported to be a tumor inhibitor in a variety of cancers, involving in many cellular processes." (PMID 34022894, 2021). "This study established the foundation for future research on the role of the LINC00261/FOXA2 axis in LC tumorigenesis by describing its capacity for tumor suppression." (PMID 34022894, 2021). "In view of the fact that LINC00261 can be promoted by the demethylation of promoter region, we summarized the roles of LINC00261, a tumor suppressor gaining increasingly important status, in cancer research." (PMID 34022894, 2021). "We found LINC00261 to be significantly upregulated in four NEPC PDX tumor lines compared with 13 hormone‐naïve tumor lines (P = 0.0102)." (PMID 33793068, 2021). "To reveal the molecular mechanism through which LINC00261 exerts its tumor suppressive function, we first determined the subcellular location of LINC00261." (PMID 33122827, 2021). "To further discover the mechanisms through which LINC00261 exerts tumor suppressive functions, we performed an RNA pulldown assay followed by mass spectrometry and found that IGF2BP1 was a binding protein of LINC00261." (PMID 33122827, 2021). "Compared to expressions in normal gastric tissue and para cancerous tissue, LINC00261 expression was found to be downregulated in GC, and low LINC00261 expression was correlated with tumor stage, lymphatic metastases, and tumor invasiveness." (PMID 34022894, 2021). "As a tumor suppressor, LINC00261 contributes to modulating cancer-cell biology via multiple molecular mechanisms (e.g., cell proliferation, apoptosis, invasiveness, migration, chemoresistance, and tumorigenesis)." (PMID 34022894, 2021). "LINC00261 has been extensively reported as a tumor suppressor involved in cell proliferation, migration, invasion, and chemoresistance in multiple cancers, such as lung cancer, gastric cancer, and colorectal cancer." (PMID 33122827, 2021). "Previous studies suggested that LINC00261 negatively regulates cellular proliferation of LUAD by activating the DNA damage response function as a tumor suppressor." (PMID 34336859, 2021).
tumor (continued). "The results showed that the expression of MALAT1, LINC00943 and LINC00261 was significantly higher in the tumour tissues than in the healthy tissues (p = 0.0243, p = 0.0005, p < 0.0001, respectively)." (PMID 32993558, 2020). "Significant downregulation of LINC00261 in tumor samples was correlated with lymphatic metastasis, tumor size, tumor stage, and patient survival." (PMID 32587768, 2020). "The decrease in LINC00261 expression was correlated with greater tumor size, higher TNM stage (III-IV), and worse survival in patients with HCC." (PMID 31448221, 2019). "LINC00261 plays a role as a tumor suppressor in GC because it weakens the stability of Slug proteins and subdues the EMT." (PMID 31448221, 2019). "In the present study, LINC00261 was found downregulated in tissue samples and NSCLC cell lines, and the expression of LINC00261 was significant correlated with tumor size, tumor stage, lymph node metastasis and patients' prognosis." (PMID 31772674, 2019). "Analysis of clinicopathological features in those patients demonstrated that downregulated LINC00261 obviously correlated to tumor size, lymph node metastasis and tumor stage." (PMID 31772674, 2019). "There are some parallels between tumor progression and early stages of endoderm differentiation, where LINC00261/DEANR1 acts in cis by recruiting the EMT-associated transcription factors SMAD2/3 to the FOXA2 promoter." (PMID 30597925, 2018). "Together, our findings suggest that linc00261 acts a tumour suppressor in GC by decreasing the stability of Slug proteins and suppressing EMT." (PMID 27878953, 2017). "Using an in vivo animal model, we revealed that linc00261 exerts tumour‐suppressive effects by inhibiting tumour metastasis." (PMID 27878953, 2017). "To further confirm the tumour‐suppressive function of linc00261, we performed an in vivo tail vein metastasis assay using nude mice." (PMID 27878953, 2017). "In this study, we report that linc00261 was significantly down‐regulated in GC tissues and the expression level of linc00261 negatively correlated with advanced tumour status and clinical stage as well as poor prognostic outcome." (PMID 27878953, 2017). "We confirmed that linc00261 down‐regulated Slug by decreasing the stability of Slug proteins and that the tumour‐suppressive function of linc00261 can be neutralized by Slug." (PMID 27878953, 2017). "We also revealed that linc00261 exerts tumour‐suppressive activity, at least in part, through reducing Slug protein abundance." (PMID 27878953, 2017). "In tumor tissues, decreased LINC00261 levels increase miR105-5p activation." (PMID 40136629, 2025). "Additionally, the miR-148a/WNT10b axis inhibits tumor growth and enhances sensitivity to cisplatin when the expression levels of LINC00261 are elevated through its interaction with WNT10b (wingless-type MMTV integration site family, member 10B)." (PMID 40136629, 2025). "Recently, emerging research suggests that Linc00261 is a tumor suppressor in various cancers." (PMID 35465017, 2022). "In summary, we identified LINC00261 as a tumor suppressor with clinical significance." (PMID 33122827, 2021). "In summary, LINC00261 overexpression impeded the growth of PC tumours in vivo." (PMID 34541823, 2021). "Additionally, LINC00261 has been shown to reduce tumor-cell invasiveness by inhibiting the epithelial-mesenchymal transition (EMT)." (PMID 34022894, 2021). "Therefore, increased expression of LINC00261 suppressed Notch signaling pathway to exert tumor suppression function in HCC." (PMID 34022894, 2021). "Mechanistically, LINC00261 may interact with NME1 (a known tumor suppressor) mRNA as protection against degradation, resulting in higher NME1 levels and increased tumor suppression." (PMID 34022894, 2021). "Overexpression of LINC00261 significantly suppressed tumor growth." (PMID 33122827, 2021). "LINC00261 functions as a tumour suppressor in PC through the miR‐222‐3p/HIPK2/ERK axis." (PMID 34541823, 2021).
tumor (continued). "Overexpression of LINC00261 regulates downstream miR-522-3p to play an anti-tumor role, which may provide potential new molecules and new targets for clinical treatment of HCC." (PMID 33928038, 2021). "LINC00261 has been reported as a tumor suppressor in multiple cancers." (PMID 33122827, 2021). "Therefore, LINC00261 overexpression exerted an inhibitory effect on the proliferation, migration, invasion of tumor cells and tube formation ability of vascular endothelial cells." (PMID 33013201, 2020). "Additionally, the expression of MALAT1, LINC00943 and LINC00261 was significantly higher in the tumour tissues than in the adjacent normal tissues (p = 0.0002, p < 0.0001, p < 0.0001, respectively)." (PMID 32993558, 2020). "Furthermore, LINC00261 is a tumor suppressor that blocks cellular proliferation by activating the DNA damage response." (PMID 31890219, 2019). "Recent studies reveal that LINC00261 participates in tumor progression in many cancers." (PMID 31772674, 2019). "In addition, miR-105 was identified as a direct target of LINC00261 via mechanism experiments and its expression in tumor tissues negatively correlated to LINC00261 expression." (PMID 31772674, 2019). "Furthermore, we found that the EMT with linc00261 knockdown can be blocked by transfection of Slug siRNA, suggesting that linc00261 exhibits tumour‐suppressive activity in GC via promoting Slug degradation and inhibiting epithelial–mesenchymal transition." (PMID 27878953, 2017). "Furthermore, both in vitro functional assays and an in vivo animal model demonstrated that linc00261 exerts tumour‐suppressive activity by reducing cancer cell invasion ability at least in part via suppressing the EMT process." (PMID 27878953, 2017). "In general, LINC00261 expression may alter tumor-cell motility in many ways." (PMID 34022894, 2021). "Functionally, the LINC00261 overexpression-induced cell proliferation and glycolysis suppression, apoptosis acceleration, and cell cycle arrest could be reversed by IGF2BP1 overexpression, suggesting that IGF2BP1 was necessary for LINC00261 to exert its tumor suppressive function." (PMID 33122827, 2021). "The findings reveal LINC00261 as a pivotal regulator in mitigating PC aggressiveness, making it a potential therapeutic target for inhibiting EMT and tumor metastasis in PC." (PMID 40136629, 2025). "Its inhibitory effect is attributed to downregulation of the micro RNA522 gene and upregulation of Long Inergenic Non-Protein Coding RNA 261 (LINC00261), which plays a role as a regulator of tumor suppressor genes." (PMID 36296934, 2022). "Finally, as reported in methods, we overlapped these lists, in order to obtain a set of potential tumor-suppressor lncRNAs (i.e., DLEU1, LINC00261, LINC00483, LINC01207, MCF2L-AS1) and oncogene lncRNAs (MEG3, RUNX1-IT1, and TP73-AS1) to experimentally analyze." (PMID 33552987, 2020). "In addition, to determine the role of N1DARP in the LINC00261-mediated tumor-suppressive signaling pathway, we generated two LINC00261 overexpression cell models with or without the start codon mutant of N1DARP (LINC00261-N1DARPwt and LINC00261-N1DARPmut)." (PMID 37714834, 2023). "In prostate cancer, the overexpression of LINC00261 was shown to inhibit the transcription of dickkopf-related protein 3 (DKK3) by recruiting GATA binding protein 6 (GATA6), resulting in the inhibition of tumor angiogenesis; this action was reversed by silencing DKK3." (PMID 34022894, 2021). "Moreover, the effect of the overexpression of the LINC00261 on the self-renewal ability, cell invasion, drug resistance, and tumorigenicity of PANC-1 stem cells was assessed by means of cell sphere formation assay, Transwell assay, cytotoxicity test, and tumor xenograft in nude mice." (PMID 34446696, 2021).